APLP2 (amyloid beta precursor like protein 2)
Diseases named in the same sentence as APLP2 in open-access papers (continued):
Sharing a sentence is not in itself a finding about the gene and the disease.
pancreatic cancer (continued). "Our published immunoblotting studies indicated elevated APLP2 expression in human pancreatic cancer cells, and by immunohistochemistry we had demonstrated increased APLP2 presence in primary human pancreatic tumors and metastases relative to the normal pancreas." (PMID 33810510, 2021). "Furthermore, it was found that pancreatic cancer migration diminished after β-2M knockdown, which also downregulated the expressions of APLP2 in PANC-1 and S2-013." (PMID 34066808, 2021). "We had previously shown that inducible knockdown of APLP2 (via shRNA) was able to delay tumor development, reduce tumor burden, and decrease metastases to the diaphragm, kidney, and intestine in an orthotopic implantation model of pancreatic cancer." (PMID 33810510, 2021). "To be able to gauge the impact of APLP2′s presence in the pancreas on the progression of pancreatic cancer, we also employed in this current study a KPC mouse model with/without expression of the Aplp2 gene in the pancreas (i.e., conditional, pancreas-specific knockdown of APLP2)." (PMID 33810510, 2021). "These published findings support a role for APLP2 in pancreatic cancer pathogenesis and also raise the question of whether APLP2 contributes to pancreatic cancer development." (PMID 33810510, 2021). "Transient knock-down of APLP2 or APP reduced pancreatic cancer cell growth and viability." (PMID 26840089, 2016). "Since APLP2 influences pancreatic cancer cell invasion and migration, we investigated whether down-regulation of APLP2 expression influenced the structure of the actin cytoskeleton in pancreatic cancer cells." (PMID 25576918, 2015). "Furthermore, we evaluated an APLP2-positive primary pancreatic cancer tissue with a matched lung metastasis, as well as a matched liver metastasis, and both of the metastatic lesions were positive for APLP2 expression." (PMID 25576918, 2015). "In this study, we observed elevated expression of APLP2 in human pancreatic cancer metastases." (PMID 25576918, 2015). "The findings in our current research demonstrating high APLP2 expression in pancreatic cancer metastatic lesions from patients suggest that APLP2 may facilitate the ability of these cancer cells to metastasize." (PMID 25576918, 2015). "Our finding that APLP2 knockdown has a very disruptive influence on actin structure within pancreatic tumors in vivo is particularly significant, since it has two implications for the development of novel therapies for pancreatic cancer." (PMID 25576918, 2015). "Amyloid precursor-like protein 2 (APLP2) is aberrantly expressed in pancreatic cancer." (PMID 25576918, 2015). "Furthermore, we have shown that APLP2 assists pancreatic cancer cell survival and growth in vitro, and treatment of pancreatic cancer cells with beta-secretase inhibitors decreases both APLP2 cleavage and cell growth." (PMID 25576918, 2015). "Of the 21 patients assessed for APLP2 expression in primary pancreatic tumors with matched liver metastases, 8 of 21 patients (38.1%) had positive APLP2 expression in both the primary tumor and the liver metastasis, whereas a lesser percentage (5 of 21, or 23.8%) had negative expression in both." (PMID 25576918, 2015). "Because growth inhibition was still observed when either APLP2 or APP was downregulated, APLP2 expression does not compensate for loss of APP in pancreatic cancer cell growth, and vice versa." (PMID 22797723, 2012). "Reduced cleavage of other proteins (in addition to APLP2) might also contribute to the ability of the β-secretase inhibitors to affect pancreatic cancer cell viability." (PMID 22797723, 2012). "By immunostaining, we also examined whether APLP2 expression was increased in human pancreatic cancer tissue, relative to normal tissues." (PMID 22797723, 2012).
pancreatic cancer (continued). "Overall, these studies suggest that APLP2 undergoes extensive modification and cleavage in pancreatic cancer cell lines, APLP2 (and APP) facilitate pancreatic cancer cell growth, and treatments that block APLP2 cleavage can diminish the growth of pancreatic cancer cells." (PMID 22797723, 2012). "Cumulatively, our findings that APLP2 functions contribute to migration and metastasis, together with our previous discovery of the ability of beta-secretase inhibition to lessen pancreatic cancer cell growth, suggest that APLP2 could be a viable target for attacking pancreatic cancer." (PMID 25576918, 2015). "Thus, strategies that reduce either APLP2 expression or processing may have a therapeutic impact on deadly pancreatic cancer metastases." (PMID 25576918, 2015). "Thus, the extensive GAG modification of APLP2 in pancreatic cancer cells may have a pro-migratory influence." (PMID 22797723, 2012). "Finally, inhibitors of β-secretase reduce APLP2 cleavage and pancreatic cancer cell viability." (PMID 22797723, 2012). "Additionally, elevated APLP2 levels were confirmed in human pancreatic cancer tissue." (PMID 22797723, 2012). "In studies utilizing pancreas-specific heterozygous and homozygous knockout of APLP2 in the KPC mouse model background, we observed significantly prolonged survival and reduced metastatic progression of pancreatic cancer." (PMID 33810510, 2021). "Furthermore, this study, as well as our previous one, highlights the involvement of APLP2 expression and its correlation with disease aggressiveness, since increased APLP2 expression correlates with a moderately or poorly differentiated stage of pancreatic cancer." (PMID 25576918, 2015). "Fourth, down-regulation of APLP2 and/or APP impairs the growth of a pancreatic cancer cell line, and each protein likely contributes to the same growth pathway, but in a unique manner." (PMID 22797723, 2012). "In both devised scenarios matching the experimental data, APLP2 and APP would have unique roles in the growth of pancreatic cancer cells." (PMID 22797723, 2012). "Overall, our results suggest that β-secretase, APLP2 (and notably its C-terminal cleavage fragments), and APP influence the survival of pancreatic cancer cells." (PMID 22797723, 2012). "Ultimately, the conclusion best fitting the data is that APLP2 and APP serve unique roles in the growth of pancreatic cancer cell lines." (PMID 22797723, 2012). "Future investigations are required to explore the possibilities of altered APLP2 or APP regulatory mechanisms and to dissect functional identities of APLP2 and APP in pancreatic cancer growth and viability." (PMID 22797723, 2012). "Given the widespread overexpression of APLP2 observed not only in pancreatic cancer but also in colon, breast, prostate, and lung cancers, TBO could exhibit a global anti-tumor effect through the inhibition of APLP2/CTFs." (PMID 38003566, 2023). "Pancreatic cancer, currently lacking definitive treatment options, exhibits elevated levels of APLP2 and its C-terminal fragments (CTFs) which are generated by BACE1." (PMID 38003566, 2023). "Our results with the novel KPC Aplp2−/−, KPC Aplp2−/+, and KPC Aplp2+/+ mouse strains will promote the pursuit of additional studies to validate APLP2 as a target for utilization in new efforts to treat pancreatic cancer." (PMID 33810510, 2021). "We have previously shown that the growth of pancreatic cancer cells, but not non-transformed pancreatic cells, is diminished by chemical inhibitors of beta-secretase, an enzyme that generates APLP2 C-terminal fragments." (PMID 25576918, 2015). "In contrast, of the 5 patient tissues in this series that were negative for APLP2 (in primary and liver lesions), 4/5 and 1/5 were assessed as exhibiting well differentiated and moderately differentiated stages of pancreatic cancer, respectively." (PMID 25576918, 2015).
pancreatic cancer (continued). "Six of 21 (28.6%) had positive APLP2 expression in their primary pancreatic tumors but not in the corresponding liver metastases." (PMID 25576918, 2015). "Within this tumor microarray, APLP2 staining in all of the 3 normal pancreas samples was negative or weak, whereas approximately half (53%) of the 17 primary pancreatic tumors were strongly positive for APLP2 and only 6% were negative." (PMID 25576918, 2015). "Second, C-terminal fragments are more consistently generated from APLP2 rather than APP in pancreatic cancer cell lines." (PMID 22797723, 2012). "Therefore, it is probable that APLP2 and APP act through the same pathway to promote the growth of pancreatic cancer cells." (PMID 22797723, 2012). "C-terminal fragments of APP were only abundantly observed in the BxPC3 cell line in our panel of pancreatic cancer cell lines, suggesting that cleavage of APLP2, rather than APP, is a consistent molecular feature of pancreatic cancer cell lines." (PMID 22797723, 2012). "Downregulation of APLP2 and/or APP in the pancreatic cancer S2-013 cell line, which displays representatively low expression of APP C-terminal fragments, decreased cell proliferation, suggesting a role for both family members in the growth of pancreatic cancer cell lines." (PMID 22797723, 2012). "Our data indicate that inhibitory therapies that target APLP2, APP and BACE may be promising for the treatment of pancreatic cancer." (PMID 22797723, 2012). "In addition to APLP2, APP was expressed in each of the pancreatic cancer cell lines." (PMID 22797723, 2012). "This process has been particularly noted in the BxPC3 pancreatic cancer cell line, which has been reported to exhibit a high level of APP cleavage; however, the accompanying expression and cleavage of APLP2 in this cell line was not examined." (PMID 22797723, 2012). "In conclusion, our studies demonstrate that abundant APLP2, but not APP, C-terminal fragment expression is conserved in pancreatic cancer cell lines; however, APP and APLP2 equally regulated the growth of S2-013 pancreatic cancer cells." (PMID 22797723, 2012). "Finally, treatment with inhibitors of β-secretases, enzymes that cleave APLP2 or APP to release C-terminal fragments, decreased the growth and viability of the pancreatic cancer cell line S2-013 but not of a non-transformed pancreatic ductal cell line." (PMID 22797723, 2012). "Simultaneous downregulation of both APLP2 and APP did not enhance growth inhibition beyond down-regulation of APLP2 or APP alone, signifying that APLP2 and APP likely act upon the same pathway in pancreatic cancer cell growth (eliminating the scenarios in the bottom half of Table I)." (PMID 22797723, 2012).
myopia (8 papers, 2015 to 2022). "Sequence variants in APLP2, a myopia susceptibility gene, have interactive effects with reading time in association with longitudinal changes in refractive errors." (PMID 35327754, 2022). "Targets of γ-secretase include APP (amyloid precursor protein) and APLP-2 (amyloid beta precursor-like protein-2); the latter protein has been linked to myopia development through an interaction with time spent reading." (PMID 31073882, 2019). "Another related protein strongly associated with high myopia, amyloid β-like protein 2 (APLP2), was significantly increased after three weeks of stress (Fig. S2Bii)." (PMID 31659173, 2019). "Previously, we reported that expression of APLP2 was strongly associated with myopia in a primate model." (PMID 26313004, 2015). "In summary, we have identified APLP2 as a novel gene involved in refractive eye development and associated with human myopia." (PMID 26313004, 2015). "In 2015, APLP2 was identified as a myopia susceptibility gene." (PMID 35327754, 2022). "Importantly, APLP2 was found to play an important role in gene-environment interaction underlying the development of childhood myopia." (PMID 34107987, 2021). "An important role of the amyloid signaling pathway, which we found to be involved in the regulation of susceptibility to myopia, is in agreement with our recent finding that a component of the amyloid signaling pathway APLP2 regulates susceptibility to myopia in mice and humans." (PMID 31362747, 2019). "Here, we used such “systems genetics” approach, combining gene expression profiling in an animal model of myopia, statistical evidence for association with myopia from two GWAS studies, and functional evidence from a gene-targeted mouse model, to identify APLP2 as one of the “missing” myopia genes." (PMID 26313004, 2015). "Furthermore, Aplp2 also strongly influenced refractive eye development and myopia susceptibility in the gene-targeted mouse model of myopia." (PMID 26313004, 2015). "Here, we present genetic and functional evidence identifying amyloid beta (A4) precursor-like protein 2 (APLP2), which was previously found to be involved in synaptic plasticity and transmission in the central nervous system, as one such myopia-susceptibility gene." (PMID 26313004, 2015). "Functional analysis of APLP2 using an APLP2 knockout mouse model confirmed functional significance of APLP2 in refractive development and implicated a potential role of synaptic transmission at the level of glycinergic amacrine cells of the retina for the development of myopia." (PMID 26313004, 2015). "In contrast, APLP2 has recently been identified as one of the myopia genes and APLP2-KO mice develop high degrees of hyperopia." (PMID 27267879, 2016). "APLP2 was first found to be differentially expressed in the retina of monkeys with experimentally-induced myopia." (PMID 26313004, 2015). "Further work will be required to pinpoint the causal variant(s) at the APLP2 locus that determine susceptibility to myopia, and to elucidate whether (as suggested by the location of the most strongly associated variant in the promoter region of the gene) they alter the level of APLP2 expression." (PMID 26313004, 2015). "APLP2 was found to be overexpressed in myopia and suppressed in hyperopia." (PMID 26313004, 2015). "The reduced susceptibility to myopia in mice lacking Aplp2 makes lowering the level of APLP2 in the retina via gene therapy an appealing future direction for therapeutic intervention in human myopia." (PMID 26313004, 2015). "Furthermore, mouse studies revealed that lack of Aplp2 has a dose-dependent suppressive effect on susceptibility to form-deprivation myopia, providing a potential gene-specific target for therapeutic intervention to treat myopia." (PMID 26313004, 2015).
breast carcinoma (4 papers, 2016 to 2021). "APLP2 decreases HLA class I surface expression on MDA-MB435S cells (formerly classified as breast cancer cells but recently classified as melanoma cells)." (PMID 26840089, 2016). "Omission of exon 7 removes the Kunitz protease inhibitor domain, and the frequency with which this APLP2 exon is excluded was found to vary in a comparison of two human breast cancer lines (MCF7 and MDA-MD-231) and human mammary epithelial cells." (PMID 26840089, 2016). "The expression of β-2M is maintained or elevated in renal cell carcinoma, oral squamous cell carcinoma, breast cancer, and prostate cancer, and studies have shown β-2M/HLA class I heavy chain/peptide complex binds APLP2 in PANC-1 and S2-013 cells that are involved in migration." (PMID 34066808, 2021). "APLP2 is differentially spliced in breast cancer cell lines and human mammary epithelial cells." (PMID 26840089, 2016). "Additionally, induction of apoptosis markers such as cleaved caspase 3 and the PARP cleavage product were also noted in the breast cancer cell lines in which APLP2 expression had been knocked down, especially in those cell lines that had been identified as having higher metastatic potential." (PMID 26840089, 2016).
colon cancer (4 papers, 2015 to 2021). "APLP2 expression was also demonstrated to be elevated in colorectal cancer, and APLP2 knockdown increased the susceptibility of HCT116 colon cancer cells to an apoptotic stimulus." (PMID 25576918, 2015). "Consistent with the findings obtained in studies of APP, knock-down of APLP2 reduced proliferation of the Caco2 colon cancer cell line." (PMID 26840089, 2016). "In colon cancer cells, APLP2 expression is positively correlated with expression of human leukocyte antigen-B-associated transcript 3 (Bat3)." (PMID 26840089, 2016).
Ewing sarcoma (4 papers, 2016 to 2025). A small round cell tumor that lacks morphologic, immunohistochemical, and electron microscopic evidence of neuroectodermal differentiation. "Our laboratory has previously shown that Ewing’s sarcoma cell lines’ expression of APLP2 increases their resistance to radiation and lysis by immune cells." (PMID 40265027, 2025). "A reduction in MHC class I molecule expression after γ radiation has been described in Ewing’s sarcoma cells due to reciprocal activation of amyloid precursor-like protein 2 (APLP2)." (PMID 35681710, 2022). "APLP2 overexpression also reduces the level of MHC class I molecules at the plasma membrane of Ewing's sarcoma cell lines." (PMID 26840089, 2016). "Upon radiation treatment, increased expression of APLP2 reduces the proportion of Ewing's sarcoma cells in the sub-G1 stage (i.e., the apoptotic subset)." (PMID 26840089, 2016). "In cell lines derived from the pediatric cancer Ewing's sarcoma, APLP2 is typically overexpressed." (PMID 26840089, 2016). "Consistent with APLP2's ability to increase Ewing's sarcoma cell survival following radiation treatment, higher APLP2 overexpression was found in Ewing's sarcoma cells that had resisted lysis by lymphokine-actived killer cells (which destroy target cells by an apoptotic mechanism)." (PMID 26840089, 2016). "APLP2 interferes with radiation-induced apoptosis and reduces MHC class I expression; APLP2 is increased in immune-evasive Ewing's sarcoma cells." (PMID 26840089, 2016).
melanoma (4 papers, 2012 to 2026). A malignant, usually aggressive tumor composed of atypical, neoplastic melanocytes. "Together with the conserved secretome profile, we found other proteins involved in protein aggregation, such as APP, APLP2, and APLP1, secreted by melanoma in a cell line‐specific manner." (PMID 32749065, 2020).
prostate carcinoma (4 papers, 2010 to 2022). A carcinoma that arises from epithelial cells of the prostate gland. "APP protein and APLP2 mRNA are overexpressed in many tumors, including cancers of the prostate, breast, colon, thyroid, lung, nasopharynx, and gastrointestinal tract." (PMID 35875068, 2022). "Five other PS up-regulated genes (MERTK13, APLP2, CLDN 3, DUSP6 and TFPI) have been found to be overexpressed in prostate cancer and many other tumor types, but their role in tumor biology is less understood." (PMID 20500816, 2010).
lung carcinoma (3 papers, 2012 to 2023). "Expression analysis reveals that hypoxia induced lung cancer related biomarkers, HIF and its modulating proteins (TGM2, CSNK1A1, CTNNA1, NAMPT/Visfatin, TNFRSF1A, ETS1, SRC-1, FN1, APLP2, DMBT1/SAG, AIB1 and AZIN1) are significantly down regulated." (PMID 23122428, 2012).
pancreatic adenocarcinoma (3 papers, 2012 to 2021). "PanIN 2 lesions exhibited moderate staining for APLP2, while PanIN 3 and pancreatic adenocarcinoma samples showed strong staining of APLP2 with ~90–100% of cells positively stained (particularly ductal epithelial cells)." (PMID 33810510, 2021). "Our data from human samples and mouse models point to the importance of APLP2 in cancer and signify the importance of APLP2 as a pro-tumor factor in pancreatic adenocarcinoma development." (PMID 33810510, 2021). "We investigated the expression of APLP2 in human patient samples of pancreatic adenocarcinoma using RNA-Seq technology." (PMID 33810510, 2021). "By immunohistochemistry, we also analyzed the expression of murine APLP2 in normal and pancreatic adenocarcinoma tissues acquired from KPC mice." (PMID 33810510, 2021). "The first implication is that APLP2 itself may be a potential therapeutic target for pancreatic adenocarcinoma." (PMID 25576918, 2015).